CXCR4 (C-X-C motif chemokine receptor 4)
Diseases named in the same sentence as CXCR4 in open-access papers (continued):
Sharing a sentence is not in itself a finding about the gene and the disease.
HIV-1 infection (continued). "A CXCR4 inhibitor would inhibit this viral envelope-CXCR4 interaction and aid in limiting HIV-1 infection." (PMID 35008248, 2021). "We have previously reported that ezrin expressed in target cells is required for efficient CXCR4-tropic HIV-1 infection." (PMID 32411688, 2020). "Susceptibility to HIV-1 infection requires the co-expression of CD4 and either CCR5 (R5) or CXCR4 (X4) receptors on the cellular surface." (PMID 32576602, 2020). "AMD3100 is a bicyclam small molecule drug that was initially developed as a treatment against CXCR4-tropic HIV-1 infection but failed during long term application studies." (PMID 32994431, 2020). "This is consistent with our previous observation that HIV-1 infection of HeLa-CD4/CXCR4/CCR5 cells upregulates the expression of miR-500a-5p, miR-34c-3p, and miR-381-3p but not miR-93-3p." (PMID 32127461, 2020). "For example, the μ-opioid agonist DAMGO (C26H35N5O6) was found to downregulate CXCR4 expression and prevent HIV-1 infection of BM HSPCs." (PMID 32154191, 2020). "Previously, we have reported that expression of ezrin in target cells is required for CXCR4-tropic HIV-1 infection, and expression of ezrin in HIV-1-producing cells is required for infectivity of released HIV-1 particles." (PMID 32411688, 2020). "The dimeric EPI-X4 derivative WSC02x2 showed a Ki of 69 nM, which is ~ tenfold lower than that of the endogenous peptide and reflects also its enhanced potency in inhibiting CXCR4-tropic HIV-1 infection and CXCL12-dependent cell migration." (PMID 32994431, 2020). "These probes will aid future discovery and characterization of CXCR4-targeting small molecules with clinical applications for HIV-1 infection, tumor metastasis, and other human diseases mediated by CXCR4." (PMID 31412600, 2019). "In another case, recombination in gp120 entailed the coreceptor switch to CXCR4, despite the recent acquisition of HIV-1 infection in 2012 confirmed by CD4+ T-cell count and viral load measure at diagnosis." (PMID 31031735, 2019). "To determine the susceptibility of CD161+ CD4+ T cells to HIV-1 infection, we first quantified the expression level of the coreceptors CCR5 and CXCR4 from HIV-1-negative and -positive individuals receiving or not receiving ART." (PMID 31594817, 2019). "For example, SDF-1/CXCR4 plays roles in immune, hematopoietic, brain development, angiogenesis, HIV-1 infection, autoimmune diseases, cancer, inflammation and other pathological processes." (PMID 31540474, 2019). "Our study provided a new approach, employing substitution of wild-type CXCR4 with a functional mutant instead of destroying the integrity of the genome to inhibit X4-tropic HIV-1 infection." (PMID 29872154, 2018). "The CXCR4/SDF-1 axis plays an important role in many human diseases including HIV-1 infection, inflammatory diseases, and cancer." (PMID 29844860, 2018). "The results indicated that the level of p24 gradually increased during HIV-1 infection and the cells (clone #9) with CXCR4 P191A resulted in partial reduction compared with wild-type cells." (PMID 29872154, 2018). "These authors further reported that the miR-146a upregulation by AMD3100 treatment or PLZF silencing decreases CXCR4 protein expression and prevents HIV-1 infection in monocytic cell line and CD4+ T lymphocytes." (PMID 29426337, 2018). "We further confirmed that the seamless replacement of wild-type CXCR4 with the P191A mutation caused significant inhibition of HIV-1 infection in TZM-b1 cells, and that the mRNA level of the mutant was comparable to wild-type CXCR4." (PMID 29872154, 2018). "As the co-receptor is important for HIV-1 entrance, the dysregulation of CCR5 or CXCR4 significantly affects HIV-1 infection." (PMID 29426337, 2018). "CCR5 and CXCR4 represent the major HIV-1 co-receptors, however CXCR4 tropism insurgence occurs during HIV-1 infection, while CCR5 is the most exclusively used co-receptor in primary infections." (PMID 29382912, 2018).
HIV-1 infection (continued). "Together, these data suggested that disruption of CXCR4 in HIV-1 reporter cell lines by lentivirus transduction renders cells resistant to X4-tropic HIV-1 infection." (PMID 29141633, 2017). "In contrast to CXCR4, a co-receptor in HIV-1 infection, the dominant co-receptor CCR5 having only a single NFKB-binding site and high dissimilarity in promoter architecture exhibited uncorrelated expression with both F3 and the LTR." (PMID 28462923, 2017). "Although HIV-1 strains use CCR5 as a major coreceptor when establishing initial infections, CXCR4 is also a coreceptor for CXCR4-tropic HIV-1 infection in vivo." (PMID 29141633, 2017). "In our previous study, the two targeting CXCR4 sgRNAs and Cas9 efficiently inhibited HIV-1 infection in CD4+ T cells." (PMID 28904745, 2017). "Here, we propose that CXCL14 stabilizes preferred conformations of CXCR4 for HIV-1 infection, possibly by promoting conformational changes in CXCR4 aggregates." (PMID 28360196, 2017). "Our results will help to guide the design of allosteric modulators specific for CXCR4 to modulate tissue repair processes, cancer, or HIV-1 infection." (PMID 28360196, 2017). "It has been shown that CD63 controls the trafficking of CXCR4, an HIV-1 receptor, and modulates the cellular susceptibility to CXCR4-tropic HIV-1 infection." (PMID 28900422, 2017). "We first evaluated CCR5 and CXCR4 expression on T cells, two chemokine receptors that additionally permit HIV-1 infection." (PMID 29312291, 2017). "The association between emergence of CXCR4-tropic HIV-1 variants (X4 variants) and disease progression of HIV-1 infection has been reported." (PMID 28472121, 2017). "CXCR4 is a chemokine receptor involved in cancer metastasis and inflammatory diseases, as well as HIV-1 infection." (PMID 29258235, 2017). "We found that GHOST-X4 cells transduced with lentiviral SaCas9/sgRNA #8 or #9 became negative for GFP expression compared to control cells, indicating that lentiCRISPR/SaCas9-mediated genome modification of CXCR4 protects GHOST-X4 cells from HIV-1 infection." (PMID 29141633, 2017). "In summary, our results demonstrated that CXCR4 disruption in CD4+ T cell lines using lentiviral vectors expressing SaCas9/sgRNAs results in resistance to HIV-1 infection." (PMID 29141633, 2017). "Using HIV-1 challenge assays, we demonstrated that CXCR4-tropic or CCR5-tropic HIV-1 infections were significantly reduced in CXCR4- and CCR5-modified cells, and the modified cells exhibited a selective advantage over unmodified cells during HIV-1 infection." (PMID 28904745, 2017). "The SDF-1 and CXCR4 axis plays an important role in many human diseases including HIV-1 infection, inflammatory diseases, and tumorigenesis." (PMID 26954567, 2016). "Intriguingly, the human immunodeficiency virus (HIV-1) has usurped CXCR4’s unique CXCL12 binding site, exploiting CXCR4 as a co-receptor in later stages of HIV-1 infection, and CXCR4 antagonists have been explored as treatments for HIV infection." (PMID 27005825, 2016). "It has been shown that Mtb can promote HIV-1 infection by increasing the expression of CXCR4 and CCR5, the two HIV-1 co-receptors and increase the susceptibility of CD4+ T cells to HIV-1 infection through a TLR2-mediated pathway." (PMID 27004401, 2016). "All these data demonstrate that the #6 or #7 gRNA/Cas9 can disrupt CXCR4 gene in Jurkat T cells, resulting in the protection against HIV-1 infection." (PMID 26481100, 2015). "Taken together, these results demonstrated that both #6 and #7 gRNA mediated Cas9 cleavage of CXCR4 can protect Ghost X4 cells against HIV-1 infection." (PMID 26481100, 2015). "To identify reasons for the high susceptibility of CD4+ T cells from the elderly to HIV-1 infection, we examined the cell surface expression levels of the primary CD4 receptor and the CCR5 and CXCR4 co-receptors, needed for HIV-1 entry." (PMID 26452480, 2015).
HIV-1 infection (continued). "Alternately, CXCL12 impairs HIV-1 infection by CXCR4 tropic virus by competitively binding CXCR4 and blocking interactions with gp120." (PMID 26579077, 2015). "To determine the efficiency of CXCR4-gRNA/Cas9 modification in providing protection to primary CD4+ T cells against HIV-1 infection, we infected the cells (containing modified CXCR4) with CXCR4-tropic HIV-1NL4-3 and cultured for 7 days." (PMID 26481100, 2015). "CXCR4 is a co-receptor for the human immunodeficiency virus type 1 (HIV-1) infection and has been considered as an important therapeutic target for AIDS." (PMID 26481100, 2015). "We observed the complete loss of GFP expression in the CXCR4-edited cells compared to control cells which contain 55.3% GFP positive cells, suggesting a limited HIV-1 infection in the cells with modified CXCR4." (PMID 26481100, 2015). "The precise and efficient genome editing of CXCR4 will provide a new strategy for therapeutic application against HIV-1 infection." (PMID 26481100, 2015). "After inhibition or disruption of CXCR4 in primary lymphocytes using siRNA or ZFNs, the CD4+ T lymphocytes became capable of resisting CXCR4-tropic HIV-1 infection." (PMID 26588898, 2015). "The biallelic inactivation of CXCR4 by lentivirus-mediated delivery of CRISPR/cas9 constructs rendered the modified cells resistant to HIV-1 infection." (PMID 26481100, 2015). "HIV-1 infection is characterized by an ongoing replication leading to T-lymphocyte decline which is paralleled by the switch from CCR5 to CXCR4 coreceptor usage." (PMID 25785610, 2015). "It is known that CCR5-tropic viruses are predominant in patients, while CXCR4-tropic viruses occasionally emerge at the end stage of HIV-1 infection." (PMID 25807049, 2015). "PLD1i inhibited CXCR4-tropic HIV-1 infection by nearly 75% in CD4+ T cells from four independent donors." (PMID 26020637, 2015). "We show that Ghost X4 cells modified with #6 or #7 gRNA/Cas9 lentivirus were negative for GFP expression compared to control cells, indicating that CRISPR/Cas9-mediated genome editing of CXCR4 protects Ghost X4 cells from HIV-1 infection." (PMID 26481100, 2015). "When pDC were depleted prior to HIV-1 infection, the induction of IFN-I and interferon-stimulated genes (ISGs) were abolished during acute HIV-1 infection with either a highly pathogenic CCR5/CXCR4-dual tropic HIV-1 or a standard CCR5-tropic HIV-1 isolate." (PMID 25077616, 2014). "Although the role of the CCR5 and CXCR4 co-receptors in HIV-1 infection is well established, little is known regarding the regulation of their expression." (PMID 23634877, 2013). "For this reason, targeted CXCR4 disruption is also being considered as an additional strategy for inhibiting HIV-1 infection." (PMID 24284874, 2013). "MDMs are susceptible to HIV-1 infection as they express both CD4 and the co-receptors CCR5 and CXCR4." (PMID 24330394, 2013). "The emergence of CXCR4-using HIV-1 viruses is associated with rapid CD4+ T-cell decline and progression from chronic to advanced stages of HIV-1 infection." (PMID 24041034, 2013). "Previously, we have demonstrated that pre-stimulation of resting CD4 T cells with anti-CD4/CXCR4 beads triggers cell signaling and actin reorganization that enhances HIV-1 infection of resting T cells." (PMID 23782904, 2013). "The modified CD4+ T cells proliferated normally and showed resistance to CXCR4 tropic HIV-1 infection in vitro." (PMID 24284874, 2013). "F-actin is required for CD4 and CXCR4 redistribution, and it has been shown that activated moesin promotes F-actin redistribution and CD4-CXCR4 clustering, which are required for efficient X4-tropic HIV-1 infection in permissive lymphocytes." (PMID 23251513, 2012). "Protein kinase activation by bryostatin has been shown to decrease expression of CXCR4 on lymphocytes and result in reduced HIV-1 infection." (PMID 23078780, 2012).
HIV-1 infection (continued). "Down-regulation of CXCR4 signaling with pertussis toxin has been shown to decrease actin dynamics, disrupting the remodeling of the cortical actin barrier required for HIV-1 infection." (PMID 22448282, 2012). "During HIV-1 infection, the virus itself acts as an agonist to stimulate CXCR4 and induce actin remodeling in resting cells." (PMID 22448282, 2012). "The dynasore treatment did not affect the cell surface expression of CXCR4, demonstrating that dynasore treatment attenuated the CD4-independent HIV-1 infection through a mechanism other than the suppression of CXCR4 expression." (PMID 21541353, 2011). "The objective of the present study was to screen a panel of three anti-CXCR4 specific monoclonal antibodies (mAbs) for their ability to block the HIV-1 infection using in vitro activated primary peripheral blood mononuclear cells (PBMCs)." (PMID 22018245, 2011). "The direct involvement of chemokine Co-R signaling in HIV-1 infection has been investigated soon after the identification of CXCR4 and CCR5 as obligatory entry Co-R." (PMID 21284907, 2011). "C-X-C chemokine receptor type 4 (CXCR-4), a co-receptor for HIV-1 infection, is expressed in the brain in a variety of cell types including neurons." (PMID 22016798, 2011). "The importance of chemokine receptors CCR5 and CXCR4 in HIV-1 infection was first reported in 1995/6." (PMID 21655330, 2011). "To assess the effect of SE on HIV-1 infection in T cells, we exposed CEMx-M7 cells to SE- and SE-F-treated CXCR4(X4)- and CCR5(R5)-tropic HIV-1 strains." (PMID 20573198, 2010). "Four weeks of therapy restores CCR5 expression levels, which are increased during HIV-1 infection, while CXCR4 expression levels demonstrate a modest change." (PMID 21134247, 2010). "Of note, emergence of CXCR4 use is common in HIV-1 infection of humans but exceedingly infrequent in macaques infected with SIVmac." (PMID 20865163, 2010). "With respect to conferring HIV resistance, stable knock down of HIV-1 coreceptors CCR5 and CXCR4 by the use of lentiviral vector delivered siRNAs has proved to be a promising strategy to protect cells from HIV-1 infection." (PMID 18667075, 2008). "Roles of coreceptors other than CCR5 and CXCR4 in HIV-1 infection and the pathogenesis of AIDS should be investigated further." (PMID 18577234, 2008). "It has been reported that the coreceptor functions of CCR5 and CXCR4 for HIV-1 infection can be inhibited by their ligands, RANTES and SDF-1β, respectively." (PMID 18577234, 2008). "It was reported that FPRL1 activated by the fMLF peptide or peptides derived from the Env glycoprotein gp120 of HIV-1 interferes with the coreceptor function of CCR5 and CXCR4 by down-regulating them, and as a result, these peptides prevent HIV-1 infection." (PMID 18577234, 2008). "Human cell lines that express CD4 and CXCR4 generally should support productive T cell-tropic HIV-1 infection." (PMID 18665212, 2008). "In a recent paper describing HIV-1 infection of primary mouse T cells from hCD4/CXCR4 transgenic mice, a significant pre-integration block was reported." (PMID 18446227, 2008). "SDF-1/CXCR4 interactions have been intensively investigated in immunology, especially with regard to mechanism of HIV-1 infection to T lymphocytes." (PMID 15978137, 2005). "Stable simultaneous knock down of both the coreceptors CCR5 and CXCR4 is necessary to prevent HIV-1 infection at the entry level by both R5 and X4, as well as dual tropic viral strains." (PMID 16109172, 2005). "To examine whether GPR15LG binding to CXCR4 interferes with HIV-1 infection, we incubated TZM-bl reporter cells with GPR15LG, CXCL12, AMD3100, and the CCR5 antagonist Maraviroc and subsequently infected them with CXCR4- or CCR5-tropic HIV-1." (PMID 40394646, 2025). "Also, the CRISPR/Cas9 system has been extensively utilized to disrupt CCR5 and CXCR4, two key coreceptors involved in HIV-1 infection." (PMID 40003685, 2025).
HIV-1 infection (continued). "HIV-1 infection of HeLa SX22-1 cells was inhibited by downregulation of CXCR4 expression." (PMID 39088581, 2024). "Notably, SDF-1 plays a protective role against HIV-1 infection, while CXCR4 is a key co-receptor for T-tropic human immunodeficiency virus (HIV-1) strains." (PMID 39715225, 2024). "The panel was chosen to follow the expression of markers of interest in HIV-1 infection (CXCR4), to study neutrophil activation (CD11b, CD66b, etc), immunosuppressive functions (PD-L1/PD-1), maturity (CD10) and Fc receptors (FcRs, CD16, CD32, CD64 and CD89), among others." (PMID 38384451, 2024). "In order to study the impact of hormones on the possible increase in the expression of CCR5 and CXCR4 co-receptors (which are known to play a key role in HIV-1 infection) on the cell surface, their expression levels were investigated in the presence/absence of steroid hormones." (PMID 37513727, 2023). "In addition to CCR5, CRISPR-Cas9 has been used extensively to target CXCR4 and generate cells that are resistant to CXCR4-tropic HIV-1 infection in vitro." (PMID 36015010, 2022). "Based on the functional importance of CD4 and CXCR4 receptors for HSPC transduction, we investigated the frequency of CD4/CXCR4 and CD4/CCR5 double-positive cells in cord blood and bone marrow HSPC subsets from nine donors to define subpopulations potentially susceptible to HIV-1 infection." (PMID 36230931, 2022). "Therefore, a study found that targeting two sites in CXCR4 led to ablation of CXCR4, making the modified cells resistant to X4-type HIV-1 infection." (PMID 33805113, 2021). "In summary, EBV transformation can induce B-cell susceptibility to HIV-1 infection in vitro in a CD4- and CXCR4-dependent manner, similar to IL-4 and/or CD40L stimulation of B cells and CD4 can be detected on peripheral blood B cells and lymphoma cells in EBV-associated diseases." (PMID 32576602, 2020). "Another recent study suggested that CD34+CD7+CXCR4+ cells may be depleted in response to CXCR4-tropic HIV-1 infection in a coculture of HIV-infected umbilical cord-derived CD34+ and OP9-DL1 cells (Tsukamoto, 2019b)." (PMID 32154191, 2020). "Identification and characterization of molecular ligands or probes of CXCR4 have been an intensive area of investigations as such ligands or probes are of significant clinical values for the studies and treatments of HIV-1 infection and other human diseases mediated by the receptor." (PMID 31412600, 2019). "Host-cell expression of the ezrin protein is required for CXCR4 (X4)-tropic HIV-1 infection." (PMID 30210460, 2018). "To assess the impact of the replacement of endogenous CXCR4 with mutant CXCR4 (P191A) on HIV-1 infection, we utilize a TZM-bl cell line containing a luciferase reporter driven by the HIV-1 long terminal repeat (LTR) promoter, which is used to evaluate and quantify HIV-1 infection." (PMID 29872154, 2018). "The decline of HIV-1 replication in biallelic CXCR4 gene-edited cells suggests that individuals equipped with homologous recombination of the CXCR4 P191A mutant could prevent or reduce HIV-1 infection." (PMID 29872154, 2018). "Genetic polymorphism of viral receptors is relevant to risks of HIV-1 infection, while it is still under debated whether the polymorphism of SDF1, a unique ligand for HIV-1 coreceptor CXCR4, is associated with HIV susceptibility and AIDS disease progression." (PMID 29420545, 2018). "In addition, there have been studies that have revealed a CD4 and CCR5 or CXCR4 independent method for HIV-1 infection of macrophages." (PMID 30619107, 2018). "The unique pathway facilitated by CXCL12-CXCR4 may be a major hurdle for the development of CXCR4-modified hematopoietic stem cells as the resistant cell reservoir for HIV-1 infection." (PMID 30619107, 2018). "Although more experiments are needed to clarify the exact mechanism, it is possible that CXCL14-mediated CXCR4 clustering may facilitate gp120 binding and, thus, X4 HIV-1 infection." (PMID 28360196, 2017).